MRPS35 (mitochondrial ribosomal protein S35)
Synonyms: MRP-S28; MRPS28; HDCMD11P; MDS023; mS35
Tractability: Small molecule: a structure with a bound ligand is known. PROTAC: ubiquitination databases record sites on it; its protein half-life has been measured.
Target class: Other cytosolic protein
Gene: Protein-coding gene on chromosome 12 (27,710,801 to 27,756,301, forward strand). Ensembl gene ENSG00000061794.
Subcellular location: Mitochondrion
Subcellular location (Human Protein Atlas): Mitochondria; Connecting piece; Cytosol
Pathways (Reactome):
Metabolism of proteins: Mitochondrial ribosome-associated quality control; Mitochondrial translation elongation; Mitochondrial translation initiation; Mitochondrial translation termination
Gene Ontology:
Molecular function: protein binding; RNA binding; structural constituent of ribosome
Biological process: mitochondrial translation
Cellular component: mitochondrion; mitochondrial inner membrane; mitochondrial small ribosomal subunit
Genetic constraint (gnomAD): Loss-of-function variants: 20 observed, 24.87 expected, observed/expected ratio (o/e) 0.8, 90% interval 0.56 to 1.17. The upper end of that interval is the gene's LOEUF score, 1.17, which puts it in group 5 of 6, group 1 being the genes least tolerant of losing a copy. Missense variants: 292 observed, 314.81 expected, observed/expected ratio (o/e) 0.93, 90% interval 0.84 to 1.02. Synonymous variants: 119 observed, 116.44 expected, observed/expected ratio (o/e) 1.02, 90% interval 0.88 to 1.19.
Homologues: Orthologues: chimpanzee MRPS35 (99% identical), macaque MRPS35 (93% identical), dog MRPS35 (85% identical), rabbit MRPS35 (79% identical), mouse Mrps35 (76% identical), guinea pig MRPS35 (75% identical), rat Mrps35 (75% identical), zebrafish mrps35 (59% identical), tropical clawed frog mrps35 (58% identical), Drosophila melanogaster mRpS35 (43% identical), Caenorhabditis elegans mrps-35 (36% identical).
Diseases named in the same sentence as MRPS35 in open-access papers:
MRPS35 is named in the same sentence as 4 diseases in open-access papers, as found by Europe PMC text mining. Sharing a sentence is not in itself a finding about the gene and the disease. The quoted sentences say what the papers report.
cancer (1 paper, 2024). A tumor composed of atypical neoplastic, often pleomorphic cells that invade other tissues. "Consistently, DepMap analysis revealed a strong correlation in gene effect between METTL17 and LRPPRC, MRPS9, MRPS22, and MRPS35, highlighting the significance of METTL17-associated cellular functions in cancer cell survival and ferroptosis defense." (PMID 38377789, 2024).
tumor (1 paper, 2022). "IFI27, LCN2, GAST, and SERPINA1 were downregulated after NACT in tumor cells, while OLFM4, MRPS35, MMP1 and MED21 were upregulated in tumor cells." (PMID 36474268, 2022). "The roles of MRPS35 and MED21 in tumor and immune regulation are still unknown, so further research is needed to explore the mechanism for the up-regulation of these genes and their implications for treatment." (PMID 36474268, 2022).
MRPS35 also shares sentences with these, for which no sentence is quoted: Hyperglycemia (1 paper); lung adenocarcinoma (1).